ATP13A2 (ATPase cation transporting 13A2)
Diseases named in the same sentence as ATP13A2 in open-access papers (continued):
Sharing a sentence is not in itself a finding about the gene and the disease.
Parkinson disease (continued). "At the same time, ATP13A2 mutations have been associated with the occurrence of neurodegenerative disorders called neuronal ceroid lipofuscinoses (NCLs) in patients with Parkinsonism." (PMID 25197640, 2014). "They specifically elaborate on ATP13A2, which causes a severe form of early onset Parkinsonism known as Kufor-Rakeb syndrome." (PMID 25120428, 2014). "The available evidence suggests that ATP13A2, by supporting lysosomal and mitochondrial function, helps prevent the α-synuclein aggregation associated with Parkinsonism." (PMID 25197640, 2014). "Here, we review recent advances in the emerging association of ATP13A2 mutations with Parkinsonism and NCLs." (PMID 25197640, 2014). "Other missense mutations in ATP13A2 have been identified that are associated with early-onset Parkinsonism." (PMID 24904274, 2014). "ATP13A2 mutations have been identified not only in patients with Parkinsonism, but also in patients with neuronal ceroid lipofuscinoses (NCLs)." (PMID 25197640, 2014). "Mutations in ATP13A2 have been identified in a familiar form of Parkinson's disease and more recently in NCLs suggesting that metal transporters are important, yet relatively little explored in these diseases." (PMID 23516525, 2013). "It is not yet clear how homozygous missense mutations (F182L, G504R and G877R) in ATP13A2 associated with parkinsonism potentially cause disease as they are likely to have subtle effects compared to truncations." (PMID 22768177, 2012). "Collectively, our study provides support for common loss-of-function effects of homozygous and heterozygous missense mutations in ATP13A2 associated with early-onset forms of parkinsonism." (PMID 22768177, 2012). "Here, we comprehensively examine the effects of parkinsonism-associated homozygous and heterozygous missense mutations on the protein stability, subcellular localization and ATPase activity of ATP13A2, and their effects on neuronal integrity." (PMID 22768177, 2012). "Mutations in the human homolog of YPK9, ATP13A2/PARK9, have been linked to genetic forms of early onset parkinsonism." (PMID 22457822, 2012). "Homozygous and heterozygous missense mutations in ATP13A2 are associated with early-onset forms of parkinsonism." (PMID 22768177, 2012). "Collectively, our data demonstrate that homozygous missense mutations associated with early-onset parkinsonism commonly reduce the steady-state levels of ATP13A2 consistent with reduced protein stability." (PMID 22768177, 2012). "Recently, homozygous and heterozygous missense mutations in ATP13A2 have been identified in subjects with early-onset parkinsonism." (PMID 22768177, 2012). "In addition, both miR-199a-5p and miR-182-5p were predicted to target the 3’UTR of several genes previously associated with parkinsonism, as in the cases of ATP13A2 and SCARB24." (PMID 38200052, 2024). "Loss of catp-6 in C. elegans and loss of ATP13A2 in cells derived from patients with Parkinson’s disease, impact lysosomal function by preventing lysosomal acidification and lysosomal enzyme maturation, which ultimately affects the degradative capacity of lysosomes." (PMID 35252181, 2022). "Mutations in PARK9 (ATP13A2) cause a complex phenotype with associated parkinsonism." (PMID 34305577, 2021). "Mutations in ATP13A2 are associated with lysosomal dysfunction and early onset Parkinson's disease." (PMID 27278822, 2016). "To begin to explore the potential pathogenic effects of missense mutations in ATP13A2 associated with early-onset parkinsonism, we generated expression constructs for V5-tagged human ATP13A2 harboring homozygous (F182L, G504R and G877R) or heterozygous (T12M, G533R and A746T) missense mutations." (PMID 22768177, 2012).
Parkinson disease (continued). "Five of the identified genes induce a roughly typical PD presentation [a-synuclein, parkin, PTEN induced putative kinase 1, DJ-1, and leucine-rich repeat kinase 2 (LRRK2)] while mutations of ATP13A2 (PARK9) cause Kufor–Rakeb disease characterized by both Parkinsonism and many atypical features." (PMID 23346074, 2012). "Moreover, atypical or complex parkinsonism may be due to mutations in genes such as ATP13A2, DCTN1, DNAJC6, FBXO7, PLA2G6, and SYNJ1." (PMID 35328025, 2022). "We also discuss another ATP13A2 mutation that is associated with the family of neurodegenerative disorders called neuronal ceroid lipofuscinoses (NCLs), and we propose a single pathway whereby ATP13A2 mutations may contribute to NCLs and Parkinsonism." (PMID 25197640, 2014). "Astrocytes are known to be become reactive in Parkinson’s disease that includes neuroinflammation, and several genes implicated in Parkinson’s are expressed in both astrocytes and neurons (e.g., PARK7, SNCA, PLA2G6, ATP13A2, LRRK2, PINK1, and PARK2)." (PMID 40972575, 2025). "This connection aligns with evidence that other Parkinson’s disease–associated lysosomal transporters, including TMEM175 and ATP13A2, influence lysosomal pH and ion flux." (PMID 41332754, 2025). "ATP13A2, a lysosome‐related transmembrane P5‐type ATP transportase, was first confirmed to play an important regulatory role in autophagy in Parkinson's disease." (PMID 37243374, 2023). "ATP13A2 is a lysosomal transmembrane P5B-type ATPase localized at acidic compartments, which is notably involved in SPG78 and Parkinson’s disease." (PMID 34359848, 2021). "Loci associated with rare monogenic forms of Parkinson’s disease, or more complex disorders with a prominent component of parkinsonism, also encode proteins involved in vesicle trafficking: VPS35, ATP13A2, PLA2G6, DNAJC6, SYNJ1, and VPS13C." (PMID 33556113, 2021). "Yeast PARK9 (YPK9) shares homology with human ATP13A2, which encodes a polyamine transporter implicated in juvenile forms of Parkinson’s disease." (PMID 34946185, 2021). "Strikingly, ATP13A2 mutations are not implicated in cardiovascular but in neurodegenerative diseases, such as Parkinson’s disease, indicating that ATP13A2 and ATP13A3 exert distinct (patho) physiological roles." (PMID 33310703, 2021). "We first screened colon cancer and normal tissues for differential expression of Parkinson’s disease-associated genes and identified ATP13A2, which encodes cation-transporting ATPase 13A2, as a putative marker for colon cancer." (PMID 33308286, 2020). "Studies investigating Mn-trafficking in humans suggest that Mn-induced Parkinsonism can result from mutations in SLC30A10, ATP13A2 or ZnT1019,20." (PMID 31024033, 2019). "A pathogenic link has been suggested between CLN12/ATP13A2 and Parkinsonism as they both protect neurons against α-Syn toxicity." (PMID 30651094, 2019). "At least some P5B isoforms are of vital importance for the nervous system, since ATP13A2 and ATP13A4 are linked to respectively Parkinson disease and autism spectrum disorders." (PMID 29505581, 2018). "Results and further interpretation and discussion can be found in the original research article “Atp13a2 expression in the periaqueductal gray is decreased in the Pink1 −/− rat model of Parkinson disease”." (PMID 27331115, 2016). "Another modifier of proteotoxicity identified from the same original yeast screen was YPK9, an ortholog of the human lysosomal P-type ATPase ATP13A2 (also known as PARK9), an enzyme known to be associated with early onset parkinsonism." (PMID 26190021, 2015). "Alternative mutations in the metal transporter ATP13a2 have been implicated in an NCL and early onset Parkinsonism, suggesting a common pathway, however the functions of the NCL proteins and underlying disease processes are not well understood." (PMID 24581221, 2014).
Parkinson disease (continued). "Due to the close relationship between NCLs and Parkinson’s disease, we examined the levels of Parkinson’s disease proteins, α-synuclein, and the metal transporter, ATP13a2." (PMID 24581221, 2014). "For instance, several PD genes, such as parkin, DJ-1, Pten induced kinase 1 (PINK1), or ATP13A2, contribute to early onset autosomal recessive forms of Parkinsonism." (PMID 25426138, 2014). "ATP13A2 (also known as PARK9) has been the most intensively studied human P5B ATPase, since mutations in this gene lead to juvenile onset Parkinson disease." (PMID 24130856, 2013). "While Loss-of-function of a neuronal lysosomal P-type ATPase, ATP13A2, underlies an autosomal recessive form of early-onset Parkinsonism, ATP13A2 mRNA expression is upregulated in sporadic Parkinson's disease." (PMID 20388210, 2010). "Interestingly, several upregulated DE genes were related to neurodegenerative diseases, such as genes related to Alzheimer’s disease: PSEN2, TREM2, and GAB2; Parkinson’s disease: ATP13A2 and DCTN1; and amyotrophic lateral sclerosis: TAF15 and FUS." (PMID 40877796, 2025). "Interestingly, deletion of ATP13A2 triggers inflammation by cytosolic leakage of mtDNA in cellular and zebrafish models of Parkinson's disease, thus suggesting a link between lysosomal dysfunction and inflammation." (PMID 35263007, 2022). "As increased ATP13a2 expression was reported to rescue lysosomal dysfunction in Parkinson’s disease fibroblasts, we hypothesise that upregulation of ATP13a2 in CLN6 affected sheep may similarly compensate to partially improve lysosomal function." (PMID 24581221, 2014). "Although complete knockout of the ATP13A2−/− gene during juvenile development results in embryonic death, further investigation is needed to fully understand the specific mechanisms by which ATP13A2 is implicated in the development of Parkinson's disease during growth." (PMID 40224594, 2023). "In particular, we envisage that more detailed investigations on experimental models of GBA1-, SYNJ1-, SYPH1-, TMEM230-, Parkin-, PINK1-, ATP13A2-, FBXO7- and SYT11-associated parkinsonism could provide new insight into the pathophysiological mechanisms leading to PD that may involve Rab dysfunction." (PMID 36009486, 2022). "Therefore, in this study, we first aimed to find a Parkinson’s disease family protein that is differentially expressed in colon cancer and normal tissue, and we were able to identify cation-transporting ATPase 13A2 (ATP13A2) as a putative biomarker for colon cancer." (PMID 33308286, 2020). "Importantly, silencing of endogenous α-synuclein ameliorated the toxicity in neurons depleted of ATP13A2, suggesting that ATP13A2-induced parkinsonism may be contributed by α-synuclein accumulation as a result of functional impairments of the lysosome." (PMID 23580245, 2013). "We previously studied ATP13A2-dependent BODIPY-SPM uptake in human neuroblastoma SH-SY5Y cells, a frequently used cell line in Parkinson’s disease research." (PMID 36830711, 2023). "Consistent with Parkinson’s disease and ALS pathologies, MO-induced partial Atp13a2 knockdown led to locomotor impairment, disorganized cerebellar axons, and defective MN path finding." (PMID 32435656, 2020). "Recent genome-wide association studies have revealed the correlation of more than a dozen loci (including PARK1/4, PARK2, PARK5, PARK6, PARK7, PARK8, ATP13A2, PARK15, and GBA) with familial Parkinson’s disease." (PMID 33308286, 2020). "Actually, the phenotypes of ATP13A2-related disease (KRS, NCL or HSP) have converged on dementia, spasticity, parkinsonism, ataxia, and peripheral neuropathy." (PMID 31289639, 2019). "Dogs with ATP13A2 mutations show clinical signs of NCL similar to those of KRS patients, but without parkinsonism, associated with astrogliosis and autofluorescent storage material in nervous and cardiac tissues at an average age of 6 years, progressively worsening over time." (PMID 39090150, 2024).
Parkinsonism (49 papers, 2012 to 2026). Characteristic neurologic anomaly resulting from degeneration of dopamine-generating cells in the substantia nigra, a region of the midbrain, characterized clinically by shaking, rigidity, slowness of movement and difficulty with walking and gait. "We only observed a marginally significant influence (but with high uncertainty due to the wide CI) from polymorphism in ATP13A2 (also known as PARK9) rs4920608 on the risk of developing PD and Parkinsonism." (PMID 33362685, 2020). "Mutations in ATP13A2 are also found in early onset parkinsonism, suggesting that ATP13A2 may also be relevant to PD." (PMID 29204154, 2017).
dementia (24 papers, 2011 to 2025). Loss of intellectual abilities interfering with an individual's social and occupational functions. "Moreover, ATP13A2 protein levels are increased in surviving neurons of humans with PD/dementia with LBs indicative of a putative protective function of high levels of ATP13A2." (PMID 24904274, 2014). "Since cation regulation and homeostasis are vital for neuronal function including intra- and inter-cellular signaling, the loss of transporter function of the ATP13A2 may explain the dysregulated neurotransmission and eventual dementia characteristic of CLN12 disease." (PMID 30651094, 2019). "In other forms, such as those caused by recessive mutations in the parkin (PARK2), PINK1 (PARK6), DJ-1 (PARK7), and ATP13A2 (PARK9), the phenotype is more often atypical due to younger-onset, presence of additional clinical signs (dementia, pyramidal signs), or absence of Lewy body-pathology." (PMID 21347293, 2011).
neuronal ceroid lipofuscinosis (17 papers, 2011 to 2025). "Loss-of-function mutations in ATP13A2 have additionally been reported to cause neuronal ceroid lipofuscinosis." (PMID 34194386, 2021). "Loss of ATP13A2 function is also associated with neuronal ceroid lipofuscinosis, a lysosomal storage disorder." (PMID 24904274, 2014). "In dogs and mice, loss of ATP13A2 elicits neuronal ceroid lipofuscinosis (NCL), a lysosomal storage disorder characterized by the accumulation of autofluorescent lipopigment." (PMID 24904274, 2014). "Following KRS, ATP13A2 was determined to be mutated in forms of neuronal ceroid lipofuscinosis (NCL), hereditary spastic paraplegia (HSP), and most recently amyotrophic lateral sclerosis (ALS)." (PMID 38249738, 2023). "Mutations in the ATP13A2 P5ATPases have been associated with a form of juvenile-onset parkinsonism known as Kufor-Rakeb syndrome, neuronal ceroid lipofuscinosis (NCL), and a hereditary form of spastic paraplegia (SPG78)." (PMID 32353073, 2020). "In vivo, Atp13a2 knockout mice exhibit a neuronal ceroid lipofuscinosis-like phenotype, accumulation of mitochondrial ATP synthase subunit C, α-synuclein accumulation, dopaminergic pathology and late-onset sensorimotor deficits." (PMID 34194386, 2021).
neuroblastoma (15 papers, 2016 to 2025). Neuroblastoma (NB) is the most common solid, extracranial childhood tumor. "Recently, it has been uncovered that impaired CLN12/ATP13A2 function causes oxidative-stress in human neuroblastoma cells." (PMID 30651094, 2019). "Furthermore, the impaired function of ATP13A2 has been directly linked to increased oxidative stress in human neuroblastoma cells, highlighting its critical role in cellular defense mechanisms against oxidative damage." (PMID 38800474, 2024). "Using ATP13A2 overexpression in neuroblastoma H4 cells and primary neuronal cultures, they showed that α-syn levels are decreased in association with a higher production of exosomes, confirming that ATP13A2 plays a critical role in α-syn transport mediated by exosomes." (PMID 31181865, 2019). "Our database analyses revealed that ATP13A2 is expressed to similar levels as ATP13A3 in neuroblastoma patients and, contrary to ATP13A3 and SLC3A2 expression, high expression of ATP13A2 is predictive of a better outcome in patients." (PMID 39981745, 2025). "We examined the properties of endogenous ATP13A2 activity in the human neuroblastoma SH-SY5Y cell line that is widely used in PD research as an in vitro model." (PMID 37080960, 2023). "Similarly, high ATP13A3 expression was correlated with poorer outcome in two neuroblastoma cohorts, while for ATP13A2 the opposite was observed." (PMID 39981745, 2025). "In melanoma and neuroblastoma cell lines subjected to proteotoxic stress, overexpression of full-length ATP13A2, catalytically-inactive ATP13A2, or the N-terminal domain of ATP13A2 reduces the accumulation of Ub-conjugated proteins by serving as a scaffold for trafficking intracellular cargo." (PMID 35252181, 2022). "We generated human neuroblastoma SH-SY5Y cells with stable expression of human αsyn WT (SH-SY5Y-αsyn) combined with microRNA-based short hairpin (sh)-mediated ATP13A2 KD, overexpression of ATP13A2 WT, or overexpression of the ATPase-deficient mutant ATP13A2 D508N (DN)." (PMID 33799982, 2021). "Finally, in SH-SY5Y human neuroblastoma cells, knockdown of ATP13A2/CLN12 reduces the amount and activity of CTSD/CLN10." (PMID 32430003, 2020). "This may reflect the differences in (i) endosomal localization between ATP13A3 (early/recycling endosomes) and ATP13A2 (late endo/lysosomes), (ii) cell type properties (endothelial versus neuroblastoma cells) and/or (iii) relative expression levels of ATP13A3 versus ATP13A2." (PMID 36830711, 2023). "SLC3A2, ATP13A2, ATP13A3 are abundantly expressed in neuroblastoma tumors, while ATP13A4 and ATP13A5 expression is low." (PMID 39981745, 2025). "Knockdown of ATP13A2 fragments mitochondria and increases the production of reactive oxygen species in SH-SY5Y neuroblastoma cells and primary cortical neurons from mice." (PMID 35252181, 2022). "In SH-SY5Y neuroblastoma cells, the depletion of PINK1, ATP13A2, and/or GBA resulted in cell death, as demonstrated by elevated LDH levels, decreased cell viability, and increased levels of the cleaved form of caspase-3 or Gasdermin D." (PMID 34035300, 2021). "In cultured human neuroblastoma cells (NLF cell line), overexpression of ATP13A2 results in cellular protection against high concentrations of Mn compared to mutated forms of ATP13A2 (c.546C > A/p.Phe182Leu, c.1510G > C/p.Gly504Arg and c.1537G > A/p.Asp513Asn)." (PMID 38249738, 2023). "Indeed, ATP13A2 contributes to the cellular uptake of BODIPY-SPM and BODIPY-SPD in human neuroblastoma (SH-SY5Y) cells corresponding to the substrate specificity of purified ATP13A2 for SPM and SPD." (PMID 36830711, 2023).
amyotrophic lateral sclerosis (8 papers, 2019 to 2025). Amyotrophic lateral sclerosis (ALS) is a neurodegenerative disease characterized by progressive muscular paralysis reflecting degeneration of motor neurons in the primary motor cortex, corticospinal tracts, brainstem and spinal cord. "Here, we expand the pathology of ATP13A2 through the identification and functional dissection of recessive mutations in two patients with a juvenile-onset amyotrophic lateral sclerosis compatible phenotype." (PMID 30992063, 2019).
Ataxia (8 papers, 2018 to 2024). Ataxia refers to impaired coordination of voluntary muscle movement. "Pathogenic variants in COL18A1, UFSP2, ZFYVE26, and ATP13A2 contribute to a wide range of clinical phenotypes, from ASM-resistant epilepsy and developmental delay to ataxia, intellectual disability, speech impediment, and other associated symptoms." (PMID 38783254, 2024). "More recently, ATP13A2 mutations have been described as a cause of HSP complicated by cognitive impairment, cerebellar ataxia, and axonal motor and sensory polyneuropathy (SPG78)." (PMID 33646413, 2021). "Recently, ATP13A2 mutations have been described as a cause of HSP complicated by cognitive impairment, cerebellar ataxia, and axonal motor and sensory polyneuropathy (SPG78)." (PMID 33646413, 2021).